GAS5 (growth arrest specific 5)
Diseases named in the same sentence as GAS5 in open-access papers (continued):
Sharing a sentence is not in itself a finding about the gene and the disease.
tumor (continued). "GAS5 expression was markedly decreased in the tumor tissues relative to surrounding non-cancerous tissue." (PMID 27034004, 2016). "However, the connection between the GAS5 levels and the sensitivity to EGFR-TKIs in tumor cells is unclear and remains to be elucidated." (PMID 25925741, 2015). "This in contradiction with other tumor tissues such as breast, bladder and pancreatic cancer where GAS5 expression was lower in tumor compared to non-tumoral tissue." (PMID 24885398, 2014). "Surprisingly, we found a significant six-fold (p < 0.0001) increase of GAS5 level in tumor tissue (n = 116) when compared to non-tumoral samples (n = 10)." (PMID 24885398, 2014). "In addition, GAS5 is downregulated during CRC progression and functions as a competitive endogenous RNA for miR-34a,which is involved in the regulation of GAS5-inhibited tumor cell autophagy and triggers apoptosis via the mTOR/SIRT1 pathway." (PMID 39830506, 2024). "Compared to the tumor tissues from the responders, those from the non-responders exhibited a remarkably lower expression of the lncRNA growth arrest-specific 5 (GAS5) (reduction by ~60%) but a significantly higher expression of the MDR efflux transporter ABCB1 (by > 2-fold)." (PMID 39403602, 2024). "In addition to this, the tumor-suppressing activity of GAS5 has been reported in HCC, where it acts as a negative modulator of miR-21 and various proteins involved in cancer cell invasion and migration." (PMID 39448589, 2024). "Interestingly, GAS5 was also detected in exosomes isolated from the serum of NSCLC patients, displayed a significantly low level compared with healthy controls, and correlated with tumor size and TNM stage." (PMID 37444428, 2023). "LncRNA growth arrest-specific 5 (lncRNA GAS5, GAS5), first discovered in 1988, is widely considered to be a suppressor in the proliferation, apoptosis, migration, and invasion of tumor cells via multiple mechanisms such as methylation, autophagy, and sponging target molecules." (PMID 37569470, 2023). "Therefore, both GAS5 and PCAT18 may also be proposed as potential tumor suppressor lncRNAs in GC and could be explored to be used in GC treatment." (PMID 37047267, 2023). "Also, the apparent tumor suppressor function of GAS5 does not fit with its role in promoting YB-1 translation, which is another area requiring further attention." (PMID 31632972, 2019). "Upon escaping the unfavorable condition, GAS5 expression is decreased and the “brakes” are released allowing CD133+ cells to draw upon the stored metabolites in biosynthetic pathways and jumpstart the processes required for active proliferation resulting in an aggressive tumor." (PMID 31740660, 2019). "In addition, we found that Gas5 expression exerted a negative control in tumor size and TNM staging." (PMID 29308053, 2018). "lncRNA GAS5 competes with PTEN to bind miR-21, and depletion or overexpression of lncRNA GAS5 could increase or decrease miR-21 expression, resulting in the downregulation or upregulation of PTEN level in these tumor cells." (PMID 30217221, 2018). "But the expression of GAS5 in NSCLC tumor tissues might not be a direct evidence of LNM (OR = 0.516, 95% CI: 0.229–1.164, P = 0.111)." (PMID 29163187, 2017). "Surprisingly, GAS5 was expressed at higher level in tumor tissue compared to non-tumoral tissue." (PMID 24885398, 2014). "In addition, GAS5 controls critical signaling pathways like PI3K/AKT/mTOR, which are fundamental to cancer progression.Furthermore, GAS5 can enhance radiosensitivity by modulating DNA damage responses or influencing the cellular process in the tumor microenvironment." (PMID 39958058, 2025). "Moreover, co-incubation of exosomal GAS5 with CD4+ T cells inhibited their differentiation into an IFN-γ-producing Th1 phenotype, skewing it towards an IL-4-producing Th2 phenotype, in part by downregulating the transcription factor T-bet, which may promote tumor cell survival." (PMID 40429961, 2025).
tumor (continued). "Growth Arrest Specific 5 (non-protein coding) (GAS5) is a small nucleolar RNA host gene, acting as a tumor suppressor, probably by favoring apoptosis." (PMID 33546468, 2021). "It is identical to GAS5 and HCG11, which located on chromosome 6q22.2 and was down-regulated in tumor tissues compared with non-tumor tissues in both databases." (PMID 30037351, 2018). "The examination showed that decreased GAS5 expression was tightly correlated with more advanced tumour-node-metastasis (TNM) staging and larger tumour size but not lymph node metastasis." (PMID 28099146, 2017). "Interestingly, when the patients were classified into two categories determined by tumor extra-prostatic extension or Gleason score > 8, Stage I-IIIA and Stage IIIB-IV, only LINC01578 and GAS5 were not significant higher expressions in high-grade tumors." (PMID 36514044, 2022). "GAS5 was confirmed to inhibit tumour cell proliferation and promote cell apoptosis, and these processes were modified by cyclin-dependent kinase 6 (CDK6), which had a negative correlation with GAS5 in BCa progression." (PMID 33968736, 2021). "This lncRNA is a transcript of the growth arrest-specific 5 (GAS5) gene, a non-protein coding gene, which was first isolated in 1988 in a search for novel tumour suppressors by subtractive cDNA cloning of genes which are preferentially expressed in growth-arrested cells." (PMID 26198250, 2015). "Along with the observation that the CD133+ cells in a tumor had an active PPP, we also detected that irrespective of whether the cells have endogenously high expression of CD133 or CD133+ population was enriched by microenvironmental cues, these cells always had an overexpression of GAS5." (PMID 31740660, 2019).
cancer (346 papers, 2011 to 2026). A tumor composed of atypical neoplastic, often pleomorphic cells that invade other tissues. "Dysregulation of GAS5 (growth arrest-specific 5 lncRNA) was linked to autoimmune, cardiovascular, and neurological diseases, as well as cancers, in the framework of abnormal cell growth, proliferation, and survival." (PMID 40725772, 2025). "This study provides a comprehensive pan-cancer analysis of GAS5, revealing its multifaceted roles as a diagnostic, prognostic, and therapeutic biomarker across different malignancies." (PMID 39958058, 2025). "GAS5 polymorphisms, particularly rs145204276 (a 5-bp ins/del in its promoter region), affect the gene’s transcriptional activity and are associated with cancer susceptibility." (PMID 40243746, 2025). "GAS5 functions as a competing endogenous RNA (ceRNA) or molecular sponge for oncogenic microRNAs (miRNAs), such as miR-21, implicated in several cancers." (PMID 39958058, 2025). "The Growth Arrest-Specific 5 (GAS5) gene encodes one of the most extensively studied lncRNAs in cancer." (PMID 40521240, 2025). "Growth arrest‐specific 5 (GAS5) is a lncRNA that is closely associated with the regulation of malignant tumors." (PMID 37506155, 2023). "Clinically, GAS5 was suggested to have value as a diagnostic biomarker and as a therapeutic target in several cancers as well." (PMID 38137519, 2023). "Recently, a GAS5 gene encodes tumor suppressor LncRNA (Growth arrest-specific 5) reported to be involved in developing many cancers, such as lung, prostate, colorectal, and breast." (PMID 37858151, 2023). "The aberrant expression of GAS5 is associated with several diseases, including various cancers, neurological disorders, and bone diseases." (PMID 36672566, 2022). "GAS5 levels are significantly reduced compared to normal controls, causing the proliferation, migration, and invasion of cancer tissues." (PMID 35837102, 2022). "A recent study identified GAS5 as a mitochondria-associated lncRNA, sustaining homeostasis by regulating mitochondrial metabolic enzymes in physiology and cancer." (PMID 35957809, 2022). "Cancer cells with low express-mutated GAS5 in cervical tissue represent a survival advantage; on the contrary, its overexpression weakens the malignant biological behavior of cervical cancer (CC)." (PMID 35837102, 2022). "In terms of cancer recurrence risk, lncRNA GAS5 rs17359906 and rs1951625 G genotype were significantly associated with high recurrence rates after chemotherapy." (PMID 34199840, 2021). "The initial analysis in CTRP dataset suggested that more GAS5 expression was associated with high docetaxel sensitivity in cancer cell lines." (PMID 34094978, 2021). "In numerous types of cancer, it has been shown that reduced GAS5 expression was associated with unfavorable clinical and pathological characteristics related to advanced stages of the disease, making it a marker for poor prognosis." (PMID 35054253, 2021). "Regarding the real-world cancer database, both the GTEx and TCGA found that a higher expression of GAS5 is associated with the alteration of head and neck tissues." (PMID 33925911, 2021). "The interaction between the miR-21 and two long non-coding RNAs, (lncRNAs) Growth arrest-specific 5 (GAS5) and cancer susceptibility candidate 2 (CASC), proved crucial in determining cisplatin resistance in cells." (PMID 33803151, 2021). "For example, the gene encoding the evolutionary conserved lncRNA Growth Arrest Specific 5 (GAS5) hosts 10 different box C/D snoRNAs but only some of them are expressed at high levels in different cancers." (PMID 34775914, 2021).
cancer (continued). "SNHG1 contributes to cell growth and survival in several cancer types, and we also found it connected with other known cancer‐associated lncRNAs, such as GAS5 and SNHG6." (PMID 32460441, 2020). "GAS5 was reported to be aberrantly expressed in several cancers, and genetic susceptibility involving GAS5 plays a critical role in various cancer types." (PMID 32354045, 2020). "This polymorphism is capable of modulating Gas5 expression level and has been associated with the susceptibility to several cancer types." (PMID 32967315, 2020). "Rs145204276 was reported to affect expression of GAS5 and increase susceptibility of several cancers 24-26." (PMID 31673232, 2019). "The five prognostic genes have all been reported to be associated with human cancer, and three (GAS5, HCP5, and SNHG11) have reported associations with OC." (PMID 31182053, 2019). "GAS5 is implicated in a variety of cancers, and is shown to affect proliferation and to be a predictable prognostic marker in CRC patients." (PMID 30786859, 2019). "Previous studies have revealed that polymorphisms in the promoter region of GAS5 are associated with different types of cancers." (PMID 30902880, 2019). "Expectedly, GAS5 under expression was found to be associated with multiple types of cancer and it was found to bind some miRNAs, including miR-21, miR-222 and miR-103 sponging their inhibitory effect on their target TSGs." (PMID 30289954, 2018). "Although lncRNA GAS5 was suggested to play an important role in inhibiting cancer development, the underlying mechanism of lncRNA GAS5 is still unclear." (PMID 29229673, 2018). "Pooled results of diagnostic data analysis showed that GAS5 exhibited a sensitivity of 0.76 and specificity of 0.64 for cancer diagnosis, and an area under the curve of 0.76 (95% CI: 0.72–0.80) indicated moderate diagnostic accuracy." (PMID 29029523, 2017). "This meta-analysis aims to explore the association between GAS5 expression levels and cancer patients' prognosis." (PMID 29163187, 2017). "Five studies, including 477 cancer patients and 366 controls comprising both patients with other diseases and healthy individuals, were used to analyze the diagnostic value of GAS5 expression." (PMID 29029523, 2017). "Accumulating studies have identified GAS5 as a potential biomarker for cancer susceptibility, metastasis, as well as survival." (PMID 28977945, 2017). "We didn't perform subgroup analyses for CRC, BRC, EOC, GC, CEC, and HNSCC, because there is only one paper investigating these associations between GAS5 and OS in each cancer type." (PMID 29163187, 2017). "Well designed, larger-size, and higher-quality basic studies need to be conducted to validate the clinical value of GAS5 as a diagnostic and prognostic cancer marker." (PMID 29029523, 2017). "To date, GAS5 has been considered to act as a “riborepressor” or “miRNA sponge” that modulates the transcriptional activity of cancer-associated genes." (PMID 28293170, 2017). "Growth arrest-specific 5 is an important cancer associated lncRNA that can regulate downstream genes by binding to the transcription factor, ensuring the transcription factor can no longer bind to promoters." (PMID 25434862, 2015). "Although some previous reports have linked increased GAS5 expression to reduced cancer risk, our findings suggest that the rs145204276 del allele may enhance CRC risk in Romanian population, mainly for advanced and poorly differentiated tumors." (PMID 40243746, 2025). "Cancer: GAS5 is broadly regarded as a tumor suppressor, with its down-regulation observed across multiple cancer types and often associated with unfavorable prognosis, and it exerts anti-cancer effects by regulating the miR-21/PTEN axis." (PMID 40563948, 2025). "Moreover, the single-nucleotide polymorphisms (SNPs) of GAS5 were reported to be associated with risk of various cancers 32-35." (PMID 39239549, 2024).
cancer (continued). "In addition to GAS5 itself, the genetic polymorphism of GAS5 can influence the development of cancer and related angiogenesis." (PMID 35456391, 2022). "GAS5 has been implicated in regulating transcriptional activity of the glucocorticoid receptor and has multiple functions related to apoptosis, immune function and various cancers." (PMID 32398718, 2021). "In contrast, low levels of GAS5 are often associated with cell proliferation and cancer metastasis." (PMID 33776993, 2021). "Research identifying the specific GAS5 gene involved in hereditary UCC susceptibility may contribute to cancer progression and risk management." (PMID 32354045, 2020). "This may suggest that the SNPs of GAS5 play different roles in the susceptibility to and progression of different types of cancer." (PMID 32354045, 2020). "Therefore, a case–control study on 1078 CRC patients and 1175 matched cancer-free controls was conducted to evaluate the association of the selected genetic variants in GAS5 with the risk of CRC, and further reveal the functional mechanisms of CRC risk." (PMID 30902880, 2019). "These examples summarily argue that the lncRNA GAS5 might serve as a useful prognostic and diagnostic marker for a variety of cancers." (PMID 31533355, 2019). "Accumulating data showed that Gas5 could be implicated in the tumorigenesis and progression of many cancers and may be a useful diagnostic and prognostic cancer biomarker." (PMID 29423063, 2018). "Considering decreased GAS5 expression was associated with unfavorable survival in several other cancers, we infer the non‐significant survival difference between low‐ and high GAS5 expression patients in our study could result from sampling error." (PMID 29745062, 2018). "This meta-analysis suggests GAS5 lncRNA may be a useful diagnostic and prognostic cancer biomarker, and may be especially useful for identifying patients prone to developing lymph node or distant metastasis." (PMID 29029523, 2017). "However, due to insufficient sampling and/or methodological limitations, published studies on the association of lncRNA GAS5 with cancer are often inaccurate and/or inadequate." (PMID 29029523, 2017). "First, pooled results demonstrated that decreased GAS5 expression was associated with a shorter OS time, suggesting that GAS5 may serve as a potential independent predictive biomarker for OS in cancer patients." (PMID 29029523, 2017). "Down-regulation of GAS5 and/or its snoRNAs along with genetic aberrations at its locus were found to be associated with poor prognosis in several cancers like breast cancer, prostate cancer, leukemia, gastric cancer, cervical cancer, renal cell and Bladder cancer." (PMID 26082843, 2015). "The growth arrest-specific transcript 5 gene (GAS5) encodes a long noncoding RNA (lncRNA) and hosts a number of small nucleolar RNAs (snoRNAs) that have recently been implicated in multiple cellular processes and cancer." (PMID 24926850, 2014). "The snoRNA-encoding GAS5 has also been implicated in cancer development." (PMID 21789175, 2011). "Finally, more recent studies indicated that the expression of GAS5 might be regulated by microRNA-21, a ubiquitous miRNA associated with a plethora of cancer types." (PMID 33125686, 2021). "The molecular mechanism of cancer caused by downregulation of GAS5 still remains unknown." (PMID 32760219, 2020). "Researchers found that GAS5 helps cancer grow by interacting with other molecules such as miR-423-3p and SMARCA4." (PMID 40451925, 2025). "The lncRNA GAS5 has been widely documented as being significantly downregulated in various cancer types." (PMID 40903777, 2025). "Such tissue-specific behavior shows that there should be a pan-cancer view to understand the full biological function and clinical implications of GAS5." (PMID 39958058, 2025).